HMGB1 (high mobility group box 1)
Diseases named in the same sentence as HMGB1 in open-access papers (continued):
Sharing a sentence is not in itself a finding about the gene and the disease.
Sepsis (continued). "Elevated levels of HMGB1 in the later stages of sepsis are often associated with unfavorable outcomes, especially in patients with concurrent chronic inflammatory conditions, leading to higher mortality rates." (PMID 39201697, 2024). "In a patient study, serum-derived EVs and macrophages from sepsis patients have elevated levels of HMGB1, which activates the NLRP3 inflammasome and causes liver damage." (PMID 39770410, 2024). "When sepsis occurs, pro-inflammatory factors and high mobility group box-1 protein (HMGB1) passively released from dead cells cause the up-regulation of programmed death-ligand 1 (PD-L1) through Toll-like Receptor 2 (TLR2) on neutrophils." (PMID 39877653, 2024). "The monoclonal antibody (mAb) m2G7, targeting amino acids 53 and 63 in the A-box domain of HMGB1, has been implicated for sepsis, pancreatic islet graft transplantation, arthritis, and drug-induced liver injury." (PMID 39682695, 2024). "Clinically, HMGB1 serum serves as an important biomarker for sepsis and associated organ dysfunction onset." (PMID 39682695, 2024). "HMGB1 has been found to influence the biological function of the intestinal mucosa, and it is associated with anemia in animal models of sepsis." (PMID 39591250, 2024). "In sepsis patients, blood lactate levels correlate with high mobility group box 1 (HMGB1) levels, a type of damage-associated molecular pattern (DAMP), from activated macrophages." (PMID 39026681, 2024). "HMGB1 is a potent proinflammatory cytokine at the late stage of sepsis and is associated with delayed death from endotoxin and sepsis." (PMID 38816685, 2024). "For example, a study in rats with lipopolysaccharide sepsis demonstrated that landiolol can inhibit lung injury and reduce the expression of high mobility group protein b1 (HMGB-1), a protein associated with lung injury." (PMID 38312313, 2024). "As a DAMP, extracellular HMGB1 is tightly associated with several types of cell death in sepsis, including apoptosis, autophagy, pyroptosis, and ferroptosis, which can deeply influence macrophage function." (PMID 39372401, 2024). "Extracellular mouse/human HMGB1 serves as a potent proinflammatory cytokine and it is associated with systemic inflammation like sepsis and various other inflammatory diseases." (PMID 39341498, 2024). "High‐mobility group box 1 protein (HMGB1) is a non‐histone nucleoprotein and plays a pivotal role in inflammatory responses associated with sepsis." (PMID 38837857, 2024). "HMGB1 has been recognized as a potential novel diagnostic and prognostic marker in a broad spectrum of diseases, such as sepsis, arthritis, inflammatory bowel diseases, fibrotic diseases, and diabetes." (PMID 39830661, 2024). "HMGB1 plays a critical role in driving the inflammatory response associated with sepsis by activating various receptors and inflammatory pathways." (PMID 38474222, 2024). "In kidneys, HMGB1 has been implicated in acute kidney injury 24-27, sepsis on CKD 28, diabetic nephropathy 29, and free light chains-induced kidney injury 30, where it acts as a DAMP that amplifies inflammation and accelerates kidney damage." (PMID 37284446, 2023). "Inflammatory cytokines are linked to the progression of sepsis by causing an excessive inflammatory response, and HMGB1 functions as a proinflammatory molecule to increase the secretion of inflammatory cytokines such as TNF-α, IL-6 and IL-1β." (PMID 38026444, 2023). "Previous research highlighted the regulatory role of SIRT1 in HMGB1 under various disease conditions, such as sepsis-associated acute kidney injury." (PMID 38034869, 2023). "Previous reports indicated that the LPS-induced release of HMGB1 was associated with sepsis and that HMGB1 is an inflammatory mediator that can increase the levels of TNF-α, IL-6 and IL-1β." (PMID 38026444, 2023).
Sepsis (continued). "In another clinical study, a similar increase in plasma HMGB1 levels was observed; however, this demonstrated an association between the elevation of this molecule and sepsis severity and mortality." (PMID 37569277, 2023). "HMGB1 is a critical proinflammatory factor that has been associated with mortality in sepsis patients." (PMID 37029295, 2023). "As an important damage-associated molecular pattern (DAMP) molecule, circulating HMGB1 plays a critical role in progression and late mortality of sepsis." (PMID 34363018, 2022). "In the most severely ill patients, HMGB1 autoantibodies in sepsis models are associated with a good prognosis." (PMID 35765707, 2022). "A recent study also proposed that lactate sensor GPR81-mediated signaling decreased circulating exosomal Hmgb1 levels, highlighting a promising therapeutic target of lactate-associated signaling in polymicrobial sepsis." (PMID 36092712, 2022). "HMGB1 plasma levels are elevated in conditions associated with abnormal coagulation, including sepsis and COVID-19, where HMGB1 has been correlated with disease severity." (PMID 35874830, 2022). "miR-381-3p restores the inflammatory response and myocardial dysfunction caused by sepsis via HMGB1." (PMID 35720285, 2022). "It was reported that high levels of HMGB1 collected by sera from patients with sepsis induce loss of vascular endothelial monolayer integrity, causing the formation of F-actin stress fibers and VE-cadherin delocalization." (PMID 35269471, 2022). "HMGB1 level is an independent risk factor for sepsis and MODS in patient with severe blunt chest trauma." (PMID 35720285, 2022). "In sepsis, the circulating pathogen-associated molecular patterns (PAMPs), including LPS, can trigger hepatocytes to release HMGB1 into the bloodstream." (PMID 36189354, 2022). "HMGB1 is a damage-associated molecular pattern protein involved in several disease states, including cancer, arthritis, and sepsis; it also acts as a late mediator in endotoxemia." (PMID 35983056, 2022). "the beneficial effects of H2 treatment on sepsis and sepsis-associated organ damage are associated with the decreased levels of HMGB1 in serum and tissue." (PMID 35720285, 2022). "In comparison, pharmacological inhibition of lactate production and/or lactate receptor GPR81-mediated signaling decreases circulating exosomal HMGB1 levels, which highlights lactate/lactate-associated signaling as a promising drug target in sepsis." (PMID 34363018, 2022). "Several genetic variations in genes with immunological functions, such as CTL4, IL1-B, IL6, CD40, and HMGB1, have been reported to be associated with sepsis." (PMID 36714653, 2022). "High-Mobility Group Box 1(HMGB1) is a late inflammatory mediator associated with sepsis, malignancy, and immune disease." (PMID 34177881, 2021). "We have previously confirmed that increased level of cerebral HMGB1 is a main cause of sepsis-induced brain injury." (PMID 34512319, 2021). "It has been reported that HMGB1 is associated with a variety of diseases, including sepsis, arthritis and cancer." (PMID 33407071, 2021). "The objective of our study is to investigate the association between the plasma levels of HMGB1 and the severity and outcomes of sepsis." (PMID 33947887, 2021). "HMGB1 is released in late endotoxemia and it is closely associated with the severity and prognosis of sepsis." (PMID 34745088, 2021). "Currently, the sepsis-associated AKI model has been established by LPS to explore the roles of HMGB1 in the pathogenesis of AKI." (PMID 34616232, 2021). "Edaravone's ability to maintain average arterial pressure and prolong the survival time of neonatal mice with sepsis caused by cecal ligation and perforation was partly attributed to its prevention of HMGB1 elevation." (PMID 33140586, 2021). "In summary, plasma levels of HMGB1 were associated with severity and prognosis of patient with sepsis." (PMID 33947887, 2021).
Sepsis (continued). "MiR-381-3p restored the inflammatory response and myocardial dysfunction caused by sepsis via HMGB1." (PMID 34784841, 2021). "We found a new function of circTLK1 in contributing to sepsis-associated acute kidney injury by regulating inflammation and oxidative stress through the miR-106a-5p/HMGB1 axis." (PMID 34250012, 2021). "We conclude that, as a humoral and local mediator, HMGB1 enhances brain inflammatory responses, after LPS priming, linked to sustained sepsis symptoms." (PMID 34208101, 2021). "Based on data analyses from 188 critically-ill patients and additional 77 patients with sepsis from the prospective SMC-RoCI registry, we observed that the plasma levels of HMGB1 were associated with the severity and mortality of sepsis." (PMID 33947887, 2021). "Poor sepsis prognosis is also associated with low zinc levels and the release of High mobility group box 1 (HMGB1) from activated and/or necrotic cells." (PMID 33658363, 2021). "High mobility group box 1 (HMGB1) causes microvascular endothelial cell barrier dysfunction during acute lung injury (ALI) in sepsis, but the mechanisms have not been well understood." (PMID 34745088, 2021). "The possible reason is that the researchers only analyzed early inflammation, while HMGB1 is often elevated in the late stage of sepsis, lasts for a long time, and can mediate sepsis‐associated anemia by interfering with erythropoiesis." (PMID 33140586, 2021). "Previous studies revealed HMGB1 was associated with the pathogenesis of inflammatory diseases including systemic lupus erythematosus, rheumatoid arthritis, and sepsis." (PMID 34177922, 2021). "Since extracellular HMGB1 was identified as a late proinflammatory mediator during sepsis, several studies have focused on modulating its signal to decrease sepsis-associated inflammation." (PMID 33732235, 2021). "Emerging study showed that wogonin reduced cecal ligation and puncture (CLP)-induced high-mobility group box 1 protein (HMGB1) production and HMGB1-dependent inflammation, and lowered sepsis-related morbidity and the risk of lung injury." (PMID 34906140, 2021). "Further research on the association of HMGB1 and sepsis phenotypes is necessary to determine the utility of HMGB1 as a biomarker." (PMID 33947887, 2021). "In this study, we aimed to investigate the effect of SphK1 inhibition on HMGB1 translocation and the underlying mechanism of sepsis-associated liver injury." (PMID 33281190, 2020). "HMGB1 expression, intracellular translocation, and acetylation were suppressed by SphK1 inhibition in sepsis-associated liver injury." (PMID 33281190, 2020). "In conclusion, SphK1 inhibition diminishes HMGB1 intracellular translocation in sepsis-associated liver injury." (PMID 33281190, 2020). "High-mobility group box-1 (HMGB1) protein has been postulated to play a pathogenic role in severe sepsis." (PMID 32498020, 2020). "Previous studies have reported that SphK1 and HMGB1 are activated in sepsis-associated liver injury." (PMID 33281190, 2020). "In the present study, we aimed to explore the effect of SphK1 inhibition on HMGB1 translocation and the underlying mechanism during sepsis-associated liver injury." (PMID 33281190, 2020). "The increased HMGB1 levels post-sepsis exert a causative role for post-sepsis complications including cognitive dysfunction and anemia in the mouse CLP model." (PMID 32265930, 2020). "We studied the mechanism underlying the effect of sesamin on the pathophysiology of sepsis through the HMGB1/TLR4/IL-33 signalling pathway." (PMID 32893702, 2020). "The prototypical damage-associated molecular pattern (DAMP) molecule HMGB1 has been shown to contribute to the pathogenesis of sepsis, traumatic shock, autoimmune diseases, cancer, as well as hepatic steatosis and fatty liver disease." (PMID 33519820, 2020). "We demonstrated that LPS-mediated subcellular localization of HMGB1 was blocked by SphK1 inhibition during sepsis-associated liver injury." (PMID 33281190, 2020).
Sepsis (continued). "Reportedly, acetylation of HMGB1 is a key process prior to its nucleus-to-cytoplasm translocation and extracellular secretion from kidney cells, accelerating the development of sepsis-associated acute kidney injury (SA-AKI)." (PMID 33029280, 2020). "In sepsis, increased circulating HMGB1 was shownto be associated with apoptosis and decreased survival rate.It is released in response to infection as an inflammatorycytokine and further stimulates an inflammatory responsewith subsequent tissue damage." (PMID 32779431, 2020). "HMGB1, one of the key damage-associated molecular patterns, is an important late-acting inflammatory cytokine of sepsis that can be actively secreted by immune cells or passively released by injured or necrotic cells." (PMID 32071292, 2020). "Generally, sulfatide successfully blocked the LPS-mediated HMGB1 release in sepsis, decreasing the level of serum HMGB1 and preventing severe symptoms and death caused by sepsis." (PMID 32655573, 2020). "In this review, we review some new insights into the roles of HMGB1 associated with inflammation, immunosuppression in sepsis." (PMID 33552058, 2020). "In conclusion, this study shows that SphK1 inhibition suppresses HMGB1 intracellular translocation in sepsis-associated liver injury." (PMID 33281190, 2020). "Studies have shown that HMGB1-specific antibodies and HMGB1 antagonists can significantly reduce the inflammatory responses and mortality associated with sepsis." (PMID 31852965, 2019). "In sepsis, increased levels were also detected for sRAGE, a soluble receptor variant blocking HMGB1/RAGE signaling." (PMID 31645609, 2019). "HMGB1 has since been identified as a pathogenic mediator during sepsis, arthritis, cancer, drug-induced liver injury and stroke, among other diseases, and inhibition of HMGB1 is beneficial in several experimental models." (PMID 30134807, 2018). "Elevation of serum HMGB1, which is released from necrotic cells and subsequently causes cell damage, was observed in patients with sepsis and ALI." (PMID 29795561, 2018). "The significant decrease in body temperature, increase in serum and splenic cytokines and in particular the high mortality rate associated with an increase in serum HMGB1 levels, would rather indicate that these mice develop sepsis." (PMID 29791477, 2018). "One notable point is that as a late-phase cytokine, the increase of HMGB1 release is tightly associated with increased mortality in animal models of sepsis." (PMID 29520271, 2018). "HMGB1 stimulates inflammatory cytokine production and creates an inflammatory cascade, which tightly associates with increased mortality of sepsis." (PMID 29520271, 2018). "HMGB1 is frequently elevated in pathological conditions like sepsis or cancer and it is therefore regarded as damage-associated pattern (DAMP)." (PMID 30574096, 2018). "HMGB1 is important in the development of sepsis-associated acute lung injury (ALI) in mice and in humans with sepsis." (PMID 29795561, 2018). "HMGB1 acts as an important damage-associated molecular pattern to respond injury, and shows intensive expression after initiation of sepsis." (PMID 29190939, 2017). "Most recently, GL was reported to prevent sepsis-induced mortality in rats, but the mechanism underlying GL regulation of HMGB1 functions in sepsis is still unclear." (PMID 28484719, 2017). "CGA-JK3 consequently interrupted IKKβ-inducible NF-κB activation and NF-κB-regulated expression of TNF-α, IL-1α or HMGB-1 gene, thereby improving TLRs-associated redundant inflammatory responses in endotoxemia, polymicrobial sepsis and ALF." (PMID 28145460, 2017). "It has been shown here that anti-HMGB1 pAb are efficacious in experimental sepsis, they alter inflammatory profiles associated with clinical lethality and do not promote immunosuppression." (PMID 28724977, 2017).
Sepsis (continued). "HMGB1 has previously been implicated in the pathogenesis of many inflammatory diseases, including sepsis, rheumatoid arthritis, chronic kidney disease, and more, all of which elicit altered states of metabolic function, including insulin resistance." (PMID 28531105, 2017). "HMGB1, a major cytokine linked to late lethality with sepsis (i.e., at 48–72 h), was elevated in three of four saline-treated CLP animals but in none of those treated with alpha-MSH or MECO-1." (PMID 29152323, 2017). "Clinical and preclinical studies have implicated HMGB1 as a mediator of sepsis pathogenesis and mortality, and thus HMGB1 represents a novel candidate for passive immune targeting in sepsis." (PMID 28724977, 2017). "In light of the pathogenic role of HMGB1 in lethal sepsis, we explored the therapeutic potential of targeting the PKM2–EIF2AK2 pathway with drugs in animal models of lethal endotoxemia and polymicrobial sepsis induced by caecal ligation and puncture (CLP)." (PMID 27779186, 2016). "HMGB1 is found to be associated with many inflammatory diseases such as cancer, trauma, arthritis, ischemia reperfusion injury, sepsis, cardiovascular shock, diabetes, and autoimmune diseases." (PMID 28101517, 2016). "Extracellular histones and high-mobility group box 1 that function as endogenous damage-associated molecular patterns (DAMPs) also contribute to the myocardial dysfunction associated with sepsis." (PMID 27011791, 2016). "A pathogenic role of HMGB-1, a molecule originally identified as a nuclear binding protein, was initially reported in sepsis and later in sepsis-associated ARDS." (PMID 29259697, 2016). "For example, the role of the endogenous TLR4 and RAGE agonist HMGB1, a molecule previously associated with sepsis, now has emerged as an important participant in mediating inflammatory and neuroinflammatory pain states." (PMID 27781082, 2016). "Our present study shows that delayed administration of human kallistatin markedly attenuated kidney, liver and lung injury in association with reduced serum levels of TNF-α, IL-6 and/or HMGB1 in mice with established sepsis." (PMID 25930108, 2015). "For instance, the presence of autoantibodies to HMGB1 in sepsis has been shown to be associated with increased survival among critically ill patients, thus indicating that the induction of autoantibodies can be beneficial in infectious diseases." (PMID 26596890, 2015). "In mouse models, sepsis-induced death that occurs several days after infection is associated with HMGB1 and is prevented by treatment with antibodies blocking HMGB1." (PMID 26695754, 2015). "Data from the present study suggests that an increased serum HMGB1 level is associated with damage of acute organ injury as shown by inflammatory histological alteration secondary to sepsis induced by CLP." (PMID 25057275, 2014). "Originally implicated as a later mediator of sepsis, recent work has shown that HMGB1 is an early mediator of injury and inflammation in liver IRI, and demonstrates a rapid increase in plasma levels following tissue reperfusion." (PMID 24410860, 2014). "In human studies, high HMGB1 level has been associated with increased mortality in subjects with severe sepsis." (PMID 24723739, 2014). "HMGB1 has been implicated in a variety of clinical conditions including arthritis, sepsis and chronic kidney disease." (PMID 24524027, 2014). "Treatment of mice with 2% hydrogen had beneficial effects on sepsis and sepsis associated organ damage, as demonstrated by decreased levels of oxidative products, increased antioxidant enzyme activity and reduced levels of (HMGB1) in serum and tissue." (PMID 25905011, 2014). "Data from some animal studies showed that high HMGB1 levels are associated with severity and lethality of sepsis." (PMID 24723739, 2014). "HMGB1, a nuclear protein released from activated macrophages or injured cells, has been implicated as an important pro-inflammatory mediator in sepsis, arthritis, and tumor-associated inflammation." (PMID 23936022, 2013).